KRAS (KRas proto-oncogene, GTPase)
Diseases named in the same sentence as KRAS in open-access papers (continued):
Sharing a sentence is not in itself a finding about the gene and the disease.
cancer (continued). "When RAS signaling is inhibited, cancer cells can escape dependency on KRAS through compensatory mechanisms involving activation of the transcriptional coactivators YAP (Yes-associated protein) and TAZ (transcriptional coactivator with PDZ-binding motif)." (PMID 41471277, 2025). "Altogether, single-cell signaling analyses with our Ras-LOCKR tools enabled the discovery of MVP’s role in facilitating the resistance of a subpopulation of cancer cells to KRas-G12C inhibitors." (PMID 39103633, 2025). "Owing to their strong oncogenic role, especially in lethal cancers such as PDAC, NSCLC, and CRC, KRAS mutations have been intensively studied over the past 40 years." (PMID 41309533, 2025). "The three Ras genes (KRAS, NRAS, and HRAS) are frequently mutated in cancer (11%, 3%, and 1% of cancers in the US, respectively), and the corresponding proteins are active when localized to the membrane." (PMID 39995872, 2025). "These alterations lead to treatment resistance, highlighting the importance of targeted therapies in KRAS-driven cancers." (PMID 40075634, 2025). "This study offers a perspective on the master activator KRAS oncogene and shared genetic and signaling pathways altered in these two aggressive cancer types, shedding light on potential actionable genes." (PMID 40013338, 2025). "Several studies have investigated the utility of siRNA to target KRAS mutants in various cancer models." (PMID 39820726, 2025). "Based on the sensitivity to BI-2493 observed in KRAS WT–amplified cancer cell lines, we suggest expanding the range of KRAS alterations that can be targeted with a pan-KRAS inhibitor and to include KRAS WT–amplified tumors." (PMID 39711431, 2025). "KRAS (Kirsten rat sarcoma two viral oncogene homolog) stands out as one of the most prevalent oncogenes across various human cancers." (PMID 39950162, 2025). "The pSMAD2L-specific gene signature comprised 351 differentially expressed genes compared to wild-type cells, which encode for cancer-associated processes such as EMT, angiogenesis, and KRAS signalling." (PMID 40319202, 2025). "This pattern suggests that KRAS mutation carriers, who typically respond poorly to TKI intended for EGFR/ALK-positive cancers, often receive chemotherapy or radiation." (PMID 40502411, 2025). "At a molecular level, KRAS is reported to be a driver gene and it is present in approximately 20% of all cancers." (PMID 41153346, 2025). "The efficacy of this approach was demonstrated by successful allele-specific editing of cancer-associated heterozygous point mutations in EGFR L858R and KRAS G12V, while minimizing editing of the corresponding wild-type alleles." (PMID 41301194, 2025). "GDC-6036 (Divarasib), another covalent KRAS G12C inhibitor, is ongoing investigated in phase 1 clinical trial for various solid tumours as both monotherapy and in combination with other anti-cancer therapies." (PMID 39820726, 2025). "Identified in 1982 as the first gene shown to be aberrantly activated in human cancer, KRAS has been the focus of intensive drug discovery efforts." (PMID 40829181, 2025). "By contrast, glecirasib exhibited very weak p-ERK inhibitory activity in non-KRAS p.G12C cancer cells, with a median IC50 value of 5,787 nmol/L (n = 3)." (PMID 40304209, 2025). "Given that Shp2 is under clinical investigation for mutant-KRAS-driven cancers, several small molecules exist for specific inhibition of this PTP26." (PMID 40419795, 2025). "Due to its high mutation frequency, overexpression, and persistent activation in cancers, KRAS has long been regarded as the “holy grail” for targeted anticancer drug development." (PMID 40427667, 2025).
cancer (continued). "Among them, Zn-DIGP bearing a zinc (II) cation in its structure was studied and properities of the theranostic fluorescent probe were observed with a down-regulation of c-MYC and KRAS expression in cancer lines (compound 37)." (PMID 41157115, 2025). "This persistent signaling contributes to the cancer’s aggressive behavior and poor prognosis, making KRAS a significant target for cancer therapy." (PMID 40501736, 2025). "AGO2 directly interacts with the oncogene KRAS; elevated AGO2 levels enhance neoplastic transformation in KRAS-driven cancers, whereas AGO2 knockout results in growth arrest." (PMID 41154621, 2025). "It was identified that the compound SIAIS562055 sustainably degraded SOS1 levels and inhibit downstream effectors, exhibiting potent antitumor activity in both KRAS-mutant cancers and BCR–ABL+ CML." (PMID 39437162, 2025). "Although the SPR results did not reflect high-affinity binding, subsequent cell-based assays demonstrated functional inhibition of KRAS signaling and reduced proliferation of KRAS-mutant cancer cell lines, suggesting potential intracellular activity." (PMID 40360486, 2025). "VT104 (also known as VT3989), an allosteric TEAD inhibitor targeting the TEAD lipid pocket, demonstrated strong preclinical efficacy in models of KRAS-mutant cancers and is currently undergoing clinical evaluation." (PMID 40649713, 2025). "Mutations in KRAS, NRAS, and HRAS are among the most frequent oncogenic alterations in human cancers." (PMID 41196374, 2025). "For example, in a murine colorectal KRAS mutant cancer model, MEKi decreased naive T-cell priming but increased antigen-specific CD8+ T-cells by protecting them from death associated with chronic T-cell receptor stimulation." (PMID 40486486, 2025). "In our cohort, most cases contained cancer-specific SNV/indel mutations, primarily KRAS and EGFR variants with significant clinical importance, with fewer instances of other variants." (PMID 40282516, 2025). "Exploring the complex domain of addressing KRAS signaling pathways and their effects in chemotherapy reveals a wide range of opportunities in various kinds of cancers." (PMID 40075634, 2025). "Mutant-KRAS-targeted cancer vaccines are emerging as a promising immunotherapeutic strategy for KRAS-mutant mCRC." (PMID 40361439, 2025). "Further SAR refinements improved solubility, reduced metabolic liabilities, and enhanced pharmacokinetics, resulting in a potent and well-balanced clinical candidate for KRAS^G12C-mutant cancers." (PMID 41041285, 2025). "This review discusses structural modifications in vitamin D3, their influence on VDR binding, transcriptional activity, and calcium homeostasis, along with their role in targeting pathways like EGFR, KRAS, and Hedgehog in cancers." (PMID 40299638, 2025). "KRAS mutations are widespread in PDAC (~85%), colorectal cancer (~45%), and lung adenocarcinoma (~30%), with lower rates in other cancers." (PMID 40805153, 2025). "In our cohort, the G12D mutation was present in most of the KRAS-altered tumors, consistent with its reported prevalence in other KRAS-altered cancer types." (PMID 40896434, 2025). "With growing insights into the biological roles of G4s in cancer, including their involvement in gene regulation and genomic stability, targeting KRAS G4 structures using small molecules represents a promising frontier in cancer therapy." (PMID 41098412, 2025).
cancer (continued). "Targeting the metabolic vulnerabilities offers a promising approach to developing effective therapies against KRAS-driven cancers." (PMID 39806421, 2025). "ACB13 is the first kind of selective, potent, and in vivo pan-KRAS degrader capable of targeting a wide range of highly prevalent KRAS-mutant cancers." (PMID 41309533, 2025). "mRNA vaccines targeting neoantigens like KRAS G12V exhibit potential in advanced cancers by generating antigen-specific T-cell responses." (PMID 40075634, 2025). "Our results demonstrate that dual siRNA-mediated silencing of KRAS and MYC is highly effective at preventing tumorigenesis beyond either siRNA alone across several cancer types and common KRAS mutations." (PMID 40762837, 2025). "Small-molecule KRAS inhibitors have emerged as promising cancer therapeutics, yet resistance development remains a major hurdle." (PMID 41436723, 2025). "The activation of NRF2 by KRAS-G12C inhibitors represents a unique example of anti-cancer drugs which positively regulate the activity of a protein which is normally considered to be an oncogene." (PMID 40890297, 2025). "The first targeted therapies for KRAS G12C-mutant cancers comprise sotorasib and adagrasib, both of which have been authorized for use in patients with previously treated NSCLC and CRC." (PMID 40940900, 2025). "Amino acids and their derivatives serve as important metabolic substrates that support KRAS-mutant cancer progression." (PMID 41184283, 2025). "Pharmacological doses of VC can effectively eradicate nearly all KRAS mutant cancer cells by modulating iron levels and oxidative stress." (PMID 40950984, 2025). "The KRAS gene, a member of the rat sarcoma viral oncogene (RAS) family, is one of the most frequently mutated oncogenes across various cancers, including NSCLC, PDAC, and CRC." (PMID 40576713, 2025). "Taken together, SIAIS562055 exhibited synergistic effects with KRAS inhibitors and overcame resistance in KRAS-mutant cancer cells, making it a promising therapeutic candidate." (PMID 39437162, 2025). "A combination of a KRAS inhibitor with an immune checkpoint inhibitor (ICI) is being investigated in clinical trial for treating cancers that are refractory to ICI-based therapy." (PMID 41294676, 2025). "As a result, ~19% of cancer patients harbor a RAS mutation, with KRAS accounting for 75% of RAS-mutant cancers, while NRAS (17%) and HRAS (7%) are associated with a smaller subset." (PMID 40801144, 2025). "Wang and colleagues, through cell and animal model studies, suggested that ST8SIA6-AS1 promotes malignant proliferation of KRAS^G12C mutant cancers by activating the Aurora A/PLK1/c-Myc pathway." (PMID 41282486, 2025). "The results are discussed for implication of precision delivery of therapeutic and imaging agents to KRAS‐mutant cancers." (PMID 39951277, 2025). "SIAIS562055 also potentiated the activity of both KRAS inhibitors in KRAS-mutant cancers and ABL inhibitors in BCR–ABL–positive CML." (PMID 39437162, 2025). "This “nuclear immunomodulation” promotes immune cell infiltration and downregulates KRAS expression, highlighting Nerofe+ldDox as a promising therapeutic approach for mtKRAS-driven cancers." (PMID 41459907, 2025). "Further preclinical studies are needed to evaluate the combination of KRASG12C inhibition with other cell-cycle inhibitors to determine if cell-cycle dysregulation is a general vulnerability in KRAS-driven cancers." (PMID 39807828, 2025). "Compared with the small-molecule SOS1 inhibitor BI-3406, SIAIS562055 led to more sustained and potent suppression of downstream signaling in KRAS-mutant cancers." (PMID 39437162, 2025). "Intriguingly, we found that NRF2, a transcriptional activator, upregulates REGγ expression in KRAS-mutant cancers." (PMID 40091835, 2025).
cancer (continued). "Kirsten rat sarcoma viral oncogene homolog (KRAS) serves as a prominent oncogenic target due to its prevalence in human cancers." (PMID 41179283, 2025). "When administered weekly intravenously to mice transplanted with KRAS G12D mutant cancer cells, it demonstrated significant antitumor effects." (PMID 41049269, 2025). "One key metabolic shift in KRAS-mutant cancers is the increased hexosamine biosynthetic pathway (HBP) flux, which boosts protein O-GlcNAcylation and N-glycan biosynthesis." (PMID 40830088, 2025). "In mice, a KRAS G12D mutation is able to promote ADM and PanIN formation and spontaneously induce invasive cancer, accelerated by an additional inflammatory trigger." (PMID 40427186, 2025). "At the single-cell level, only Golgi Ras activity (measured by Golgi Ras-LOCKR-S FRET ratios) correlated (R2 = 0.78, H358 cells) with Erk activation (pErk immunostaining) 72 h after AMG-510 treatment in the KRas-G12C-driven cancer cell lines that were tested." (PMID 39103633, 2025). "Combination strategies are concurrently being investigated to improve outcomes in KRAS-mutant cancers." (PMID 41373672, 2025). "Targeting the Hippo–YAP/TAZ axis presents a promising approach to overcoming resistance to KRAS‐targeted therapies and enhancing outcomes in KRAS‐mutant cancers." (PMID 40895190, 2025). "By combining irinotecan‐loaded silicasomes with spleen‐targeting LNPs carrying KRAS mRNA, our aim is to enhance the activation of the cancer immunity cycle and overcome the formidable immunosuppressive barriers of PDAC." (PMID 40498983, 2025). "As a key node of the cancer cell signaling pathways, KRAS plays an important role in regulating cell growth, the cell cycle, cell migration, cell survival, etc.." (PMID 40304209, 2025). "Inhibiting SOS1, a KRAS activator and crucial feedback regulator, has emerged as a promising strategy for the treatment of KRAS-driven cancers." (PMID 40362343, 2025). "This suggests that NOS2 and its substrate arginine are critical components for cancer cell survival and adaptation during anti-KRAS therapies." (PMID 40567499, 2025). "Since the knock‐down KRAS have the capacity to inhibit cellular homeostatic survival in cancer cells, the knock‐down KRAS HCC cell (SMMC‐7721) also exhibits low glycolytic metabolism." (PMID 40390765, 2025). "FTase proteins (FNTA and FNTB) as well as eight of the 116 PFPs are known cancer-relevant proteins as per COSMIC Cancer Gene Census49 or TCGA50 (KRAS, HRAS, NRAS, RHEB, RHOA, DDX3X, ARID2, and SAV1)." (PMID 39995872, 2025). "Among these variants, KRAS and PIK3CA have been previously reported as pathogenic somatic mutations in cancers." (PMID 41311737, 2025). "In summary, we propose that cancer cells that express mutant KRAS proteins and other strong oncogenes require efficient minor splicing and unencumbered expression of MIGs to support the molecular pathways they depend on." (PMID 40624356, 2025). "This strategy exploits the intrinsic metabolic fragility of KRAS mutant cells and provides an expanded therapeutic option for overcoming drug-resistant cancers." (PMID 40563591, 2025). "KRAS gain-of-function mutations, including G12D, G12C and G12V are known to activate RAF/MEK/ERK pathway in various cancer types." (PMID 41391757, 2025). "Overall, in response to oncogenic KRAS expression in cancer cells, fibroblasts activate cytokines with cognate receptors expressed in immune cells, prevalently myeloid cells." (PMID 39782689, 2025). "The formation of G4s in these key regulatory regions, such as those found in c-MYC, KRAS, and others, has been associated with reduced gene expression, further suggesting that targeting these G4 structures could serve as an effective approach for anti-cancer therapies." (PMID 40333779, 2025).
cancer (continued). "A clinical candidate BI 3706674 is now under clinical evaluation in cancers harboring KRASG12V or KRAS WT amplifications (NCT06056024)." (PMID 40829181, 2025). "LY3962673 is another non-covalent KRAS G12D inhibitor with high affinity for KRAS G12D-GDP and demonstrated robust antitumor activity in cancer cell lines and multiple KRAS-G12D-mutant patient-derived xenograft (PDX) models." (PMID 40361439, 2025). "YAP/TAZ function as essential effectors downstream of KRAS, and their activation can circumvent KRAS dependency in some cancer subtypes." (PMID 40895190, 2025). "KRAS mutations also lead to the downregulation of MHC Class I molecules, impairing the ability of CD8 + cytotoxic T cells to detect cancer cells." (PMID 40001243, 2025). "Among the RAS oncogene family, which includes KRAS, HRAS, and NRAS, KRAS is the most frequently mutated, accounting for ∼30% of all RAS-driven cancers, while HRAS and NRAS mutations are less common, occurring in ∼8% and ∼3% of cases, respectively." (PMID 40563459, 2025). "Taken together, these results suggest a convergent selection of cognate immune receptors in different patients with KRAS Q61H-positive cancers, suggesting a high epitope immunogenicity." (PMID 40165973, 2025). "Studies have shown that KRAS-mutant cancer cells exhibit sensitivity to a variety of albumin-conjugated drugs, including adriamycin, anti-EGFR antibodies, and human β-defensin-2." (PMID 40723808, 2025). "Recent advances in targeted cancer therapies have led to the development of small molecule inhibitors designed to address oncogenic RAS gene mutations, particularly regarding KRAS, which is the most frequently mutated RAS isoforms in human cancers." (PMID 40427514, 2025). "These inhibitors target key points in KRAS pathway that are commonly dysregulated in cancers, providing significant opportunities for precision medicine." (PMID 39806421, 2025). "Studies have found that the KRAS mutant cancer cells exhibit a high dependency on glutamine to support anabolic growth and proliferation." (PMID 40563591, 2025). "•The study presents a dual-targeted therapeutic strategy that combines KRAS inhibition with cytotoxic agents, potentially improving treatment efficacy and overcoming resistance in KRAS-driven cancers, such as PDAC." (PMID 40382842, 2025). "RAS genes, such as HRAS, KRAS, and NRAS, were the first identified human oncogenes and are mutated frequently in cancer." (PMID 39455281, 2025). "We demonstrate here that KRAS, including its various activating mutants, is subjected to ubiquitin-mediated proteasomal degradation in cancer cells." (PMID 40473213, 2025). "Once considered undruggable, remarkable progress in targeting oncogenic KRAS has led to more than 30 compounds now in clinical evaluation or approved for treatment of KRAS-mutant cancers." (PMID 40082410, 2025). "Pathways and network analysis revealed that most of the identified genes were enriched in KRAS‐related pathways and involved in cancer disease, the cell cycle, cellular movement, and developmental disorders." (PMID 40013338, 2025). "While well-known Ras-related oncogenes, such as KRAS, have been extensively explored, the role of other Ras-related genes in cancer remains poorly studied." (PMID 40362656, 2025). "The YAP/TAZ pathway is linked to AXL upregulation in cancer, and YAP has even been implicated as a driver of adaptive resistance to KRAS inhibitors." (PMID 39395205, 2025). "While Ras oncogenes like the Kirsten rat sarcoma viral oncogene homolog (KRAS) are well studied in cancer, our understanding of other Ras family proteins remains incomplete." (PMID 40362656, 2025). "Since oncogenic KRAS promotes cell survival and proliferation, the effect of the PCAIs on cancer cell viability was determined." (PMID 40736275, 2025).